LUNAR1 (leukemia-associated non-coding IGF1R activator RNA 1)
Gene: Long non-coding RNA gene on chromosome 15 (99,014,506 to 99,069,892, forward strand). Ensembl gene ENSG00000278090.
Diseases named in the same sentence as LUNAR1 in open-access papers:
LUNAR1 is named in the same sentence as 10 diseases in open-access papers, as found by Europe PMC text mining. Sharing a sentence is not in itself a finding about the gene and the disease. The quoted sentences say what the papers report.
colorectal cancer (4 papers, 2019 to 2026). A primary or metastatic malignant neoplasm that affects the colon or rectum. "The results showed that the proliferation, colony formation and invasion of colorectal cancer cells were significantly inhibited after the downregulation of LUNAR1, while cell apoptosis was induced." (PMID 31882986, 2019). "In the present study, we investigated the potential role of the Notch-induced lncRNA LUNAR1 in colorectal cancer (CRC)." (PMID 31882986, 2019). "Recently, LUNAR1 was found expressed in colorectal cancer (CRC), expanding the promise of LUNAR1 as a therapeutic target." (PMID 34072257, 2021). "Studies have shown that LUNAR1 inhibition significantly suppresses IGF1 signaling in CRC, and LUNAR1 may be a promising prognostic marker for clinical management of colorectal cancer." (PMID 39830506, 2024). "We sought to determine whether LUNAR1, a Notch-induced lncRNA first reported in T-ALL, plays a significant role in colorectal cancer." (PMID 31882986, 2019).
leukemia (4 papers, 2016 to 2026). A malignant (clonal) hematologic disorder, involving hematopoietic stem cells and characterized by the presence of primitive or atypical myeloid or lymphoid cells in the bone marrow and the blood. "The association of lncRNAs with several subtypes of leukemia, such as MEG3, IRAIN, and UCA1 related to AML and ANRIL, LUNAR1, in ALL, increase the possibility to use them as biomarkers for the diagnosis, prognosis, and treatment (to provide a target) for the different subtypes of this disease." (PMID 30744139, 2019).
acute lymphoblastic leukemia (3 papers, 2020 to 2021). Leukemia with an acute onset, characterized by the presence of lymphoblasts in the bone marrow and the peripheral blood. "In T-cell acute lymphoblastic leukemia (T-ALL), the Notch-regulated cheRNA LUNAR1 binds to the enhancer of IGF1R, activates the promoter of IGF1R in cis, maintains a high level of mRNA expression, and promotes the growth of T-ALL." (PMID 33937246, 2021). "Notch-regulated oncogenic lncRNA, leukemia-induced non-coding activator RNA-1 (LUNAR1), has been identified in T-cell acute lymphoblastic leukemia (T-ALL)." (PMID 32164715, 2020). "LUNAR1 is a NOTCH-regulated oncogenic lncRNA, located on chromosome 15q26.3, and specifically expressed in T cell acute lymphoblastic leukemia (T-ALL), thereby playing a crucial role in its progression." (PMID 32368311, 2020).
T-cell acute lymphoblastic leukemia (2 papers, 2018 to 2019). Acute lymphoblastic leukemia of T-cell origin. "For example, Notch 1 induced LUNAR1 could drive tumor proliferation by upregulating insulin-like growth factor receptor 1 in T cell acute lymphoblastic leukemia." (PMID 30560474, 2019). "In human T cell acute lymphoblastic leukemia (T-ALL), the lncRNA LUNAR1 is regulated by the Notch pathway and is necessary for efficient T-ALL growth through enhancement of IGF1R mRNA expression." (PMID 29403493, 2018).
acute myeloid leukemia (1 paper, 2021). Acute myeloid leukemia (AML) is a group of neoplasms arising from precursor cells committed to the myeloid cell-line differentiation. "There have identified a number of lncRNAs association with several subtypes of leukemia, such as MEG3, IRAIN, and UCA1 related to acute myeloid leukemia (AML) and ANRIL, LUNAR1, in ALL." (PMID 34101758, 2021).
Obesity (1 paper, 2019). Accumulation of substantial excess body fat. "This association suggested that LUNAR1 might be involved in obesity-related tumourigenesis and progression in CRC." (PMID 31882986, 2019). "Statistical analysis revealed that the difference in LUNAR1 levels among the normal weight, overweight and obesity groups was significant (P = 0.030)." (PMID 31882986, 2019).
tumor (9 papers, 2017 to 2026). "Upregulation of LUNAR1 in CRC is linked to antagonistic tumor characteristics, reduced overall survival and disease-free survival (DFS)." (PMID 38294554, 2024). "Because the association of LUNAR1 was found to be associated with tumour aggressiveness in clinical specimens, we next performed a transwell assay to confirm the effect of LUNAR1 on the migration and invasion of cells." (PMID 31882986, 2019). "LUNAR1 expression in CRC was found to be associated with the tumour aggressiveness, disease-free survival and overall survival of patients." (PMID 31882986, 2019). "Likewise, LUNAR1 lncRNA fold-expression level was significantly positively associated with larger tumor size (p = 0.0033) and deeper tumor invasion (p = 0.042)." (PMID 41748599, 2026). "The associations of LUNAR1 with tumour aggressiveness and clinical outcomes were evaluated." (PMID 31882986, 2019). "In addition, the associations of LUNAR1 with sex, age, tumour location, MSI, KRAS mutation, BRAF mutation, and PIK3CA mutation were not statistically significant." (PMID 31882986, 2019). "In addition, the expression of LUNAR1 in CRC was also showed to be associated with the tumour differentiation status, invasion depth, node metastasis status and TNM stage, indicating a significant role of LUNAR1 in CRC aggressiveness." (PMID 31882986, 2019). "Conversely, suppressing the prognostic marker LUNAR1 hampers tumor expansion, migration, aggression, and growth." (PMID 38294554, 2024). "Again, LUNAR1 upregulation is associated with aggressive CRC, advanced tumor stage, poor differentiation status (high grade and stage), deeper tumor invasion and TNM, being attributed to unfavorable disease-free survival as well as OS." (PMID 36229883, 2022). "In vivo experiments involving the transplantation of tumor cells into mice revealed that tumor proliferation was blocked only in mice in which LUNAR1 was inactivated." (PMID 32368311, 2020). "In CRC patients with increased LUNAR1 expression, the adjusted HR of unfavourable prognosis was 2.79 (95% CI: 1.56–4.99, P < 0.001) compared with that of patients with tumours of preserved LUNAR1 expression." (PMID 31882986, 2019). "The adjusted HR for patients with tumours of increased LUNAR1 expression was 2.81 (95% CI: 1.69–4.67, P < 0.001) compared with that of the LUNAR1 preserved group as a reference." (PMID 31882986, 2019). "Moreover, the increased expression pattern of LUNAR1 was more likely to be detected in tumours with a poor differentiation status or an advanced TNM stage." (PMID 31882986, 2019). "In this context, LUNAR1 might constitute an independent biomarker of tumour recurrence and prognosis for CRC patients and could contribute to precise diagnosis and treatment." (PMID 31882986, 2019). "Moreover, the impact of LUNAR1 on the malignant behaviour of tumour cells was tested in cell lines." (PMID 31882986, 2019). "For example, some preclinical studies have begun to focus on the potential of targeting certain specific lncRNAs to complete tumor therapy and related drug development, such as H19, HOTAIR, LUNAR1, etc.." (PMID 36837389, 2023). "In agreement with this, it has been found that the inhibition of LUNAR1 in CRC decreases tumour growth and efficiently depletes IGF1 pathway activity, indicating a role for the LUNAR1/NOTCH1/IGF1R axis in cancer development." (PMID 37628760, 2023). "The downregulation of LUNAR1 in SW620 cells inhibited cell proliferation, migration, invasion and tumour growth while inducing apoptosis." (PMID 31882986, 2019).
cancer (3 papers, 2019 to 2023). A tumor composed of atypical neoplastic, often pleomorphic cells that invade other tissues. "The results showed that the number of cancer cell colonies was decreased in LUNAR1-downregulated cells, and LUNAR1 siRNA transfection caused a higher percentage of apoptotic cells." (PMID 31882986, 2019). "As oncogenic Notch1 and over-activation of IGF1 are known to promote cancer development, LUNAR1 may be active in other cancers with Notch1 alterations." (PMID 36230680, 2022).
LUNAR1 also shares sentences with these, for which no sentence is quoted: diffuse large B-cell lymphoma (1 paper); heart failure (1).